NPM1 (nucleophosmin 1)
Diseases named in the same sentence as NPM1 in open-access papers (continued):
Sharing a sentence is not in itself a finding about the gene and the disease.
gastritis (1 paper, 2014). Inflammation of the stomach. "The NPM1 immunoreactivity was also heterogeneous in intestinal metaplastic, gastritis and inflammatory cells, which are commonly observed in GC patients." (PMID 24410879, 2014). "In all cases, the NPM1 immunoreactivity was detected in neoplastic and non-neoplastic cells, including in intestinal metaplastic, gastritis and inflammatory cells." (PMID 24410879, 2014). "However, NPM1 immunoreactivity was detected in neoplastic and non-neoplastic cells, including in intestinal metaplastic, gastritis and inflammatory cells." (PMID 24410879, 2014).
gynecological cancer (1 paper, 2024).
hepatoblastoma (1 paper, 2024). Hepatoblastoma (HB) is a malignant hepatic tumor and is the most common pediatric liver cancer. "Altogether, these observations provide ample biological rationale why panobinostat is working so efficiently in MYC/NPM1-associated hepatoblastoma cells." (PMID 39529166, 2024). "Of clinical importance, upregulation of the MYC target gene nucleophosmin 1 is indicative of response to panobinostat and associated with metastatic disease in patients with hepatoblastoma." (PMID 39529166, 2024). "We furthermore described NPM1 as a surrogate marker for MYC activation in hepatoblastoma, which we found to be predominantly expressed in metastatic hepatoblastoma, but also in many other cancers." (PMID 39529166, 2024).
histiocytic neoplasm (1 paper, 2026). Histiocytic tumors are a heterogeneous group of tumors and tumorlike masses commonly associated with histologically identical extracranial lesions. "NPM1 mutation-specific antibodies should be integrated into the diagnostic panels for MS or LC, while IRF8 and PU.1 are not recommended as they cannot distinguish MS from histiocytic neoplasms." (PMID 41781345, 2026).
Huntington ́s disease (1 paper, 2023). "NPM1 overexpression is considered a prognostic marker for the recurrence and progression of various hematological malignancies and high levels of NPM1 have been observed in specific areas of the brain in a mouse model of Huntington ́s disease." (PMID 37759327, 2023).
Insulin resistance (1 paper, 2022). Increased resistance towards insulin, that is, diminished effectiveness of insulin in reducing blood glucose levels. "Of note, the ectopic expression of NPM1 in HepG2 cells has been reported in PA-induced insulin resistance conditions and our data also corroborate mitotic cell cycle regulation by NPM1 through phosphorylation at T199 upon PA exposure." (PMID 35732625, 2022).
Lymphadenopathy (1 paper, 2013). Enlargement (swelling) of a lymph node. "The presence of NPM1 mutations was not related to age, sex, or the occurrence of fever, pallor, bleeding tendency, splenomegaly, hepatomegaly, or lymphadenopathy (p=0.39, 0.76, 0.516, 0.605, 0.217, 0.190, 0.416, and 0.230, respectively)." (PMID 24385775, 2013).
macular degeneration (1 paper, 2007). Loss of vision in the central portion of the retina (macula), secondary to retinal degeneration. "RPGRIP, RANBP2, NPM1, PDE6D, and NPHP5 were selected on the basis of protein interaction with RPGR or RPGRIP1 as these two proteins independently cause photoreceptor degeneration when mutated; ABCA4 was selected as a control gene, and because of its association with macular degeneration and RP." (PMID 17653054, 2007).
Maffucci syndrome (1 paper, 2024). Maffucci syndrome is a very rare genetic bone and skin disorder characterized by multiple enchondromas, leading to bone deformities, combined with multiple dark, irregularly shaped hemangiomas or less commonly lymphangiomas. "In the most recent version of the ISSVA classification, the NPM1 gene was indicated as being associated with Maffucci syndrome." (PMID 38778413, 2024). "Thus, we conclude that the NPM1 variant is not involved in the pathogenesis of Maffucci syndrome." (PMID 38778413, 2024).
malignant rhabdoid tumors (1 paper, 2019). "Interestingly, immunohistological analyses showed universal alteration of NPM1 in human malignant rhabdoid tumors." (PMID 31462227, 2019).
medulloblastoma (1 paper, 2019). A malignant, invasive embryonal neoplasm arising from the cerebellum. "Relatively elevated NPM1 mRNA expression in AT/RT was also confirmed by qPCR compared with medulloblastomas and normal brain tissues, including the cerebellum." (PMID 31462227, 2019).
metastatic disease (1 paper, 2024). "Interestingly, NPM1 expression was significantly higher in tumor than in normal liver tissue, especially in patients with metastatic disease, and correlated well with response to panobinostat." (PMID 39529166, 2024). "Thus, our data define NPM1 as a putative marker to predict response to panobinostat and outcome of HB patients, especially those with metastatic disease." (PMID 39529166, 2024).
Miscarriage (1 paper, 2024). A pregnancy that ends at a stage in which the fetus is incapable of surviving on its own, defined as the spontaneous loss of a fetus before the 22th week of pregnancy. "We observed that MANF co-localized and interacted with NPM1 in the nucleus of trophoblast cells from URM samples, interfering with NPM1 expression, a mechanism that may be involved in the process of miscarriage." (PMID 38164189, 2024).
Obesity (1 paper, 2022). Accumulation of substantial excess body fat. "In this study, the decreased m6A level was first detected and high expression of fat mass and obesity-associated protein (FTO) was responsible for the m6A suppression in NPM1-mutated AML." (PMID 35211409, 2022).
oligodendroglioma (1 paper, 2015). A well-differentiated (WHO grade II), diffusely infiltrating neuroglial tumor, typically located in the cerebral hemispheres. "NPM1, RKIP/PEBP1 and GRP78 expressions were significantly distinct in GBMs and oligodendrogliomas compared to AST II and NN (p < 0.0001, blocked t test), corroborating previous data of our group." (PMID 26108672, 2015).
Parkinson disease (1 paper, 2021). A progressive degenerative disorder of the central nervous system characterized by loss of dopamine producing neurons in the substantia nigra and the presence of Lewy bodies in the substantia nigra and locus coeruleus. "KEGG pathway analysis showed that the co-expression of NPM1 was primarily associated to ribosome, Parkinson disease, and RNA transport, which was like the findings of previous studies." (PMID 34335635, 2021). "KEGG pathway analysis demonstrated that the co-expression of NPM1 was primarily associated to the ribosome, Parkinson disease, and RNA transport." (PMID 34335635, 2021). "The GO/KEGG enrichment analysis indicated that NPM1 was closely related to translational initiation, ribosome, structural constituent of ribosome, ribosome, Parkinson disease, and RNA transport." (PMID 34335635, 2021).
pediatric cancer (1 paper, 2021). "Our approach has also identified other fusions commonly associated with pediatric cancer, including EWSR1-FLI1 (n = 9), FGFR1-TACC1 (n = 3), PAX3-FOXO1 (n = 3), ZFTA-RELA (n = 2), COL3A1-PLAG1 (n = 2), and NPM1-ALK (n = 2)." (PMID 34863095, 2021).
retinal diseases (1 paper, 2007). "In this study, RPGRIP1, RANBP2, NPM1, PDE6D, NPHP5, and ABCA4 genes were selected on the basis of interaction with RPGR or RPGRIP1 or their implication in related retinal diseases, and were investigated as candidate genetic modifiers of XLPRA1." (PMID 17653054, 2007).
schizophrenia (1 paper, 2018). A major psychotic disorder characterized by abnormalities in the perception or expression of reality. "Based on our data, APD-induced HSP8A and NPM1 expression might be implicated in the possible therapeutic effects of these drugs on treating schizophrenia." (PMID 29514709, 2018). "A microarray study revealed downregulation of NPM1 gene expression in the postmortem cortex of patients with schizophrenia." (PMID 29514709, 2018). "Another study also revealed downregulation of HSPA8 and NPM1 within layer 2 of the insular cortex, which is closely related to auditory hallucinations and language, in patients with schizophrenia." (PMID 29514709, 2018). "We postulate that increased expression of NPM1 and NCL might be implicated in the regulation of proteins related to the MAPK signalling pathway when patients with schizophrenia are treated with certain APDs." (PMID 29514709, 2018). "NPM1 and NCL also regulate the expression of proteins related to the MAPK signalling pathway, which is abnormally expressed in the anterior cingulate (ACC) and dorsolateral prefrontal cortex (DLPFC) of patients with schizophrenia." (PMID 29514709, 2018).
T-cell leukemia (1 paper, 2024). A malignant disease of the T-lymphocytes in the bone marrow, thymus, and/or blood. "Since CCDC28A also fuses with NUP98 to form the NUP98::CCDC28A fusion gene in T-cell leukemia, it is likely that the oncogenic activity of CCDC28A enhances the leukemic activity of NPM1::CCDC28A." (PMID 39443736, 2024).
Tumor Lysis Syndrome (1 paper, 2021). a group of metabolic abnormalities that can occur as a complication during the treatment of cancer, most commonly after the treatment of lymphomas and leukemias. "Since tumor lysis syndrome was rare; this procedure seems reasonable maybe with the exception of patients with NPM1 or IDH mutations." (PMID 33191481, 2021).
urinary system cancers (1 paper, 2023). "Except those frequent mutated genes in urinary system cancers, we also identified other less frequent mutated genes, including CSF1R (37%), NPM1 (37%), EGFR (25.9%), and NOTCH1 (22.2%)." (PMID 37515929, 2023).
vascular malformation (1 paper, 2023). A non-neoplastic disorder that is the result of defects of vascular morphogenesis. "The mutation that affects DDX24 LLPS properties can transduce its effect to the phase behavior of NPM1 and disrupt RNA biogenesis, ultimately causing vascular malformations." (PMID 37705750, 2023). "Our findings illustrate how DDX24 mutation affects nucleolar structure and function by regulating the phase behavior of NPM1 in the setting of vascular malformation." (PMID 37705750, 2023). "However, the connection between DDX24 and NPM1 in vascular malformation remains elusive." (PMID 37705750, 2023).
ZIKV infection (1 paper, 2017). "In addition, fraction of cells with absence of nucleolar NPM1 did not change after ZIKV infection except a slight increase from 0 to 3.2% in MR766-infected hNPCs at 4 dpi." (PMID 29192272, 2017).
tumor (267 papers, 2003 to 2026). "Second, we aimed to confirm the potential relevance of NPM1 mutations as a specific anti-tumor target for TCR-based immunotherapy." (PMID 40557158, 2025). "We focused on Thr199 phosphorylation of NPM1 because it is specifically implicated in regulating NPM1’s functional activity, including its involvement in cell proliferation and tumor progression." (PMID 41145488, 2025). "Although AML is typically characterized by a low mutation burden, certain high-frequency driver mutations, such as FLT3-ITD and NPM1 mutations, can generate immunogenic peptides that act as tumor-specific antigens, triggering targeted immune responses." (PMID 40861464, 2025). "Only the VAF of one NPM1‐mutation was higher in cfDNA compared to the IEM‐AML tumor (0.63 vs. 0.15%)." (PMID 40066001, 2025). "NPM1 is a nucleolar protein linked to key tumor‐promoting and tumor‐suppressing properties in various cancers." (PMID 40318146, 2025). "KEGG also showed that cell differentiation and apoptosis pathways were enriched in Npm1-deficient tumor-initiating cells." (PMID 37130348, 2023). "Mutated NPM1 collaborates with mutations in 2 other gene classes and mutations in the cohesin complex, spliceosome complex, and tumor suppressor genes functionally synergize with only one other gene class." (PMID 34944812, 2021). "Altogether, these results point to a significantly increased abundance of cytoplasmic p-NPM1 (Thr199) in tumor tissues from BRAF-mutated in comparison with wild-type BRAF CA patients." (PMID 34201061, 2021). "Our group has recently developed CAR-CIML NK cells targeting a tumor-specific neoepitope expressed on the cell surface by HLA-A2 in NPM1-mutated AML." (PMID 34863287, 2021). "This includes the consideration of stem cell transplant after first remission for the primitive subset of NPM1-mutated AML cases whose tumor cells lack a FLT3-ITD mutation." (PMID 33594052, 2021). "Anti-NPM1 CAR significantly demonstrated anti-tumor function and specific killing against NPM1-mutated AML cell lines." (PMID 34863287, 2021). "Primary AML tumor samples were selected based on having known HLA haplotypes for HLA-A, B, C and HLA-DR, and at least one or more common recurrent mutations in either NPM1, FLT3, DNMT3A, IDH1, IDH2, KIT, or RAS from previous clinical evaluation." (PMID 31291378, 2019). "Another strategy targeting mutant NPM1 in AML would be to utilize NPM1 mutated peptides as part of a vaccination approach in combination with checkpoint inhibitors to stimulate an endogenous anti-tumor response." (PMID 31291378, 2019). "A proteomic study using ES surgical samples identified high protein expression of NPM1 and confirmed that the expression was significantly associated with tumor malignancy and the prognosis in ES patients." (PMID 29581854, 2018). "We previously demonstrated that the multivalent pseudopeptide N6L binds to two major nucleoproteins, nucleolin and NPM1, and inhibited tumor growth and associated angiogenesis." (PMID 26993766, 2016). "NPM1 is frequently overexpressed, mutated, rearranged and deleted in human cancer cells, therefore it is regarded as a tumor marker." (PMID 25779011, 2015). "Restoring FBP1 expression partially reversed the tumor-promoting effects of NPM1, while the loss of FBP1 in PDAC tissues was indicative of a poorer prognosis." (PMID 26068981, 2015). "A higher NPM1 level was linked to more advanced tumor stages, grades, poor prognosis and likelihood of recurrence." (PMID 25779011, 2015). "This decrease is unlikely due to a loss of expression of the anti-NPM1 shRNA since all shNPM1 tumours preserve a 90% decrease in NPM1 accumulation." (PMID 24796332, 2014). "NPM1 (up-regulated) has been shown to be implicated in human tumourigenesis, functioning both as an oncogene and as a tumour-suppressor." (PMID 21714911, 2011).
tumor (continued). "While NPM1-derived peptides can stimulate immune responses in preclinical models and relapse settings, tumor-driven HLA loss and immune editing may limit long-term effectiveness." (PMID 40861464, 2025). "Our results suggest that mutated-NPM1-targeted CTLs may be a useful therapeutic option to control low-tumor burden relapse following conventional chemotherapy in older NPM1-mutated AML patients or eradicate persistent MRD after HSCT." (PMID 37345068, 2023). "Although there was a putative FAM84B regulated cell proliferation and tumor growth through NPM1, but the underlying molecular mechanism contributing to cell cycle pathway in ESCC remains unknown." (PMID 35396552, 2022). "Therefore, loss of NPM1 changed the tumor cell metabolism and behavior, lessening the amount of tumor proliferating cells." (PMID 34781949, 2021). "With respect to the AML-categories, a more substantial blast drop under lenalidomide was noticed in AML with defining mutations, despite the fact that the presence of driver mutations such as FLT3 and NPM1 has been linked to low cytolytic activity of the tumor microenvironment." (PMID 33704530, 2021). "In other human neoplasms, mutations in the NPM1 gene are rare." (PMID 30126426, 2018). "Nucleophosmin-1 has been implicated in several pathways including mRNA transport, chromatin remodeling, anti-apoptotic cascade and genome stability, and it is commonly overexpressed, mutated, rearranged and sporadically deleted in tumor samples." (PMID 30241282, 2018). "Nucleophosmin (NPM1) is a nucleoprotein and associated with tumor growth." (PMID 29784056, 2018). "Moreover, the persistence of NPM1 mutation was associated with a significantly higher risk of relapse.Those data suggest that ABR is a key mediator of tumor suppressor function in AML." (PMID 29262589, 2017). "NPM1 has been directly implicated in tumor progression in a number of cancers." (PMID 27259278, 2016). "In addition, tumor cells harboring KRAS mutations have shown NPM1 expression dependency." (PMID 34781949, 2021). "Interestingly, response in NPM1-mutated AML may be linked to tumor-specific immunity recovery of T-cells and HLA-presentation in the mutant protein of NPM1 (NPM1c)." (PMID 33363031, 2020). "Furthermore, to confirm whether our protein profiles were significantly associated with EWS/FLI1 onco-protein and tumor malignancy, we performed cell proliferation assays based on either NPM1 or EWS/FLI1 siRNA knockdown." (PMID 29581854, 2018). "DNA-methylation alterations frequently co-occurred with tumor suppressors (OR ≈ 4.6, p = 0.007), transcription factors (OR ≈ 3.9, p = 0.023), and NPM1 (ρ = 0.32)." (PMID 42123510, 2026). "Our data revealed that NPM1 couples major oncogenic and tumor suppressor pathways via translational control, offering a potential avenue toward targeting difficult-to-treat cancer drivers and tumor heterogeneity." (PMID 41413654, 2026). "Gene set enrichment analysis (GSEA) of WNT signatures revealed a significant correlation between WNT activation and NPM1 expression across tumor types, and within COAD/READ tumors, the cancer subtype exhibiting the strongest WNT activation." (PMID 41413654, 2026). "This stabilization of NPM1 enhances the ribosome biogenesis process and the translation of specific gemcitabine‐resistance proteins, ultimately driving tumor progression and chemoresistance." (PMID 41114465, 2026).